MBP (myelin basic protein)
Diseases named in the same sentence as MBP in open-access papers (continued):
Sharing a sentence is not in itself a finding about the gene and the disease.
autism (16 papers, 2011 to 2023). Persistent deficits in social interaction and communication and interaction as well as a markedly restricted repertoire of activity and interest as well as repetitive patterns of behavior. "Alterations in white matter development have been associated with autism manifestations, making MBP a highly interesting protein in the understanding of this effect." (PMID 31379804, 2019). "Recent studies suggest that autoantibodies to myelin basic proteins (MBP) are significantly more present in autistic children than in control subjects, suggesting that MBP is a potential candidate autoantigen in autism." (PMID 37686785, 2023). "Although without a total consensus from different research groups, it has been suggested that there is a connection between autism, serotonin, and MBP." (PMID 35328471, 2022). "A significant positive correlation between autism symptom severity scores and cerebellar MBP levels was seen in plKO males." (PMID 34400844, 2021). "↑ auto-Abs to MBP found in regressive autism compared to classic (infantile) autism and Tourette syndrome subjects." (PMID 30483058, 2018). "Serum levels of anti-MBP auto-antibodies in autistic patients and their relation to the degree of the severity of autism and hyperserotonemia." (PMID 21696608, 2011). "Nonetheless, no proposed mechanistic investigation indicates a direct link between MBP and autism." (PMID 35164154, 2022). "In addition, the mRNA levels of brain development‐related genes CHD7 and oligodendrocyte development‐related genes Olig2 and MBP were significantly decreased in the VPA‐induced autism model group (p < 0.01), and improved after AVP treatment (p < 0.01)." (PMID 36239083, 2022). "This may also involve dysfunction of myelination pathways, as shown by the finding of circulating antibodies against myelin basic protein (MBP) and myelin-associated glycoprotein (MAG) in some autism patients." (PMID 25126406, 2014). "In addition, there was a non-significant difference in the frequency of seropositivity of anti-MBP auto-antibodies between patients with severe autism (81.8%) and children with mild to moderate autism (76.5%), P = 0.46." (PMID 21696608, 2011). "Other laboratory data support the autoimmune hypothesis in the pathogenesis of autism based on the cerebrospinal fluid findings of elevated levels of autoantibodies to MBP and serological antibodies to measles virus, supporting the autoimmune pathogenesis of the disorder." (PMID 35328471, 2022). "Therefore, reduction of MBP may lead to increased Aβ peptides and brain atrophy in AD, whereas increased MBP favors myelination and brain growth in autism." (PMID 31024350, 2019). "The higher levels of MAP-2, NFP, MBP, MAG, α-synuclein S100B and GFAP (3.2 to 4.8-fold) autoantibodies reported in ASD children warrant further research for developing autoantibodies screening as a biomarker for detection of early autism." (PMID 31035713, 2019). "Autoantibodies against myelin proteins might still have prognostic value for ASD patients, since serum levels of anti-MBP and anti-MAG antibodies were shown to be increased in severe autism patients compared to patients with mild or moderate disease severity." (PMID 31379804, 2019). "In our series, there was a non-significant difference in serum levels of anti-MBP auto-antibodies between children with severe autism and patients with mild to moderate autism, P = 0.15." (PMID 21696608, 2011). "There was a non-significant difference in serum levels of anti-MBP auto-antibodies between children with severe autism and patients with mild to moderate autism, P = 0.15." (PMID 21696608, 2011). "Several studies show increased levels of autoantibodies to MBP in the sera of children with autism, implying that cerebral MBP levels may be high, although MBP has not been extensively studied in autism brain tissue." (PMID 31024350, 2019).
Cerebral ischemia (16 papers, 2009 to 2025). Restriction of arterial blood supply to the brain associated with insufficient oxygenation to support the metabolic requirements of the tissue. "Here, we detect an increase in angiogenesis and a decrease in MBP loss at 14 days after cerebral ischemia in the ADSC-EVs treated group compared to the PBS control." (PMID 35057862, 2022). "After cerebral ischemia, the ischemia and hypoxia of brain tissue can lead to oligodendrocyte death and demyelination, so caused MBP flowing into CSF." (PMID 24524292, 2014). "However, from the few available studies addressing oligodendrocyte progenitor cells and myelin components such as the myelin basic protein (MBP) after experimental cerebral ischemia, an inconsistent view on ischemia-caused alterations of oligodendrocyte structures has been emerged." (PMID 29467621, 2018). "The results showed that inducing cerebral ischemia after a week of excessive microplastic ingestion significantly reduced microtubule-associated protein 2 (MAP2) and myelin basic protein (MBP), as confirmed by immunohistochemistry." (PMID 39996714, 2025). "Cerebral ischemia negatively affects the integrity of WM, as indicated by a reduction in the signal of MBP, which serves as a marker for assessing myelin integrity." (PMID 40290135, 2025). "Similar findings have been reported in animal models of cerebral ischemia with Ro 61-8048 treatment and MBP induced EAE rats." (PMID 32505212, 2020). "Interestingly, previous findings suggested that the adult brain has a limited capacity for white matter repair; the compensatory increases in MBP is insufficient for restoring white matter integrity at day 14 after cerebral ischemia." (PMID 28840056, 2017). "However, other studies have shown the presence of smaller protein fragments in various models, including NF-L and MBP in models of traumatic brain injury and neurodegenerative autoimmunity, as well collagen IV and laminin in models of cerebral ischemia." (PMID 37342767, 2023). "This study demonstrated that increased expression of MBP and NF200 by HPC had a restorative effect on white matter damage 14 and 28 days after cerebral ischemia." (PMID 37435771, 2023). "It is reported that the numbers of MBP-positive oligodendrocytes and NG2-(Neuron/Glia Antigen 2)-positive OPCs gradually decrease with the aggravation of cerebral ischemia." (PMID 34008771, 2021). "The reverse transcription (RT)-qPCR results demonstrated that LIPUS treatment increased the expression levels of pro-differentiation-related genes (Olig2 and Sox10), as well as a significant up-regulation of myelin-related genes such as PLP, MBP, and MOG in mice with cerebral ischemia." (PMID 40290135, 2025).
depression (16 papers, 2011 to 2025). "The antidepressant effects correlated with restored MBP, CNP, and IL-1β expression levels, suggesting that MBP/CNP deficiencies in depression may involve IL-1β elevation." (PMID 40500721, 2025). "Patient samples diagnosed with depression exhibit reduced myelin content, axon numbers, and MBP expression, along with reactive gliosis in different brain regions." (PMID 39819542, 2025). "Altogether, these findings revealed that dysregulated iron metabolism mediated by FOXO1 between neutrophils and oligodendrocytes results in a decrease in MBP in oligodendrocytes, thereby contributing to the development of depression following TBI." (PMID 38556884, 2024). "In patients with depressive disorders, we revealed a significant increase in MBP, which is one of the main markers of destruction of the myelin sheath and indicates the processes of neurodegeneration." (PMID 37763190, 2023). "To translate our findings from mouse models of depression to humans, we measured the protein levels of MBP, PSD95, and EphA4 in postmortem brain samples provided by the Stanley Medical Research Institute (Rockville, Maryland, USA)." (PMID 35271507, 2022). "MBP dysfunction(s) are related with physiological reactions to stress and emotional states, nervousness, and depression in adulthood and every conceivable marker for rationalities in cerebrum injuries are accounted for in other studies." (PMID 34356152, 2021). "In a cross-sectional naturalistic study, the S100B, MBP and GFAP levels in the blood serum were compared between two diagnostic groups (patients with Depressive Episode (DE, n = 28) and patients with Recurrent Depressive Disorder (RDD, n = 21)), and healthy controls (n = 25)." (PMID 37763190, 2023). "The reversal of MBP/CNP deficits and IL-1β reduction suggests that myelin dysregulation in depression involves inflammatory-mediated oligodendrocyte impairment." (PMID 40500721, 2025). "A previous study confirmed that MBP protein immunoreactivity was decreased in individuals with SCZ and depression who died by suicide compared to psychiatrically normal controls." (PMID 38891940, 2024). "Consequently, the research pinpointed four key genes, MBP, CYP4B1, ERMN, and SLC26A7, which hold clinical relevance and exhibit potential significance in the pathophysiology of COVID-19 induced depression." (PMID 40918512, 2025). "Notably, the levels of MBP, key structural elements of the myelin sheath, were significantly decreased in mice with TBI-induced depression." (PMID 38556884, 2024). "Moreover, in the current study, running exercise significantly reversed the decrease in the percentage of MBP+ myelinated fibers and the thickness of the myelin sheath in the CA1 hippocampal subfield in the UCS-exposed depression model mice." (PMID 34880203, 2021). "In contrast to running exercise, fluoxetine failed to reverse the changes in oligodendrocyte maturation and differentiation as well as the decrease in the percentage of MBP+-myelinated fibers and the thickness of the myelin sheath in the hippocampi of UCS-exposed depression model mice." (PMID 34880203, 2021). "Significant negative correlations between the anti-PLP and anti-MBP autoantibody levels and demyelination were found for the total sample of patients and all groups separately, except for the Depression group, for which these correlations were near significant (p < 0.01)." (PMID 41465566, 2025). "Myelin pathology may occur in PTSD, depression and PCS, and MBP is essential for remyelination after damage; SNP-related alterations in the gene which codes for this key protein could thus engender variability in recovery after mechanical or non-mechanical trauma." (PMID 26251769, 2015).
ischemia (16 papers, 2014 to 2025). A hypoperfusion of the BLOOD through an organ or tissue caused by a PATHOLOGIC CONSTRICTION or obstruction of its BLOOD VESSELS, or an absence of BLOOD CIRCULATION. "In the ischemia-normothermia group, in the white matter lesions (p = 0.008) and areas of extensive diffuse MBP loss (p = 0.011), there were fewer microglia than in the intact myelin area." (PMID 35690757, 2022). "In the ischemia-normothermia lesion and extensive diffuse MBP loss areas, the number of astrocytes were significantly lower than ischemia-normothermia intact areas (p = 0.001, p = 0.007)." (PMID 35690757, 2022). "By contrast, ischemia caused downregulation of MBP expression whereas 25–200 mg/kg aspirin ameliorated ischemia-induced decreased MBP expression." (PMID 24478700, 2014). "In addition, through the SMI32/MBP immunofluorescence intensity ratio, we verified the early demyelination damage caused by ischemia on cerebral WM and the ameliorating effect of LIPUS on early myelin loss." (PMID 40290135, 2025). "The proportion of gitter cells relative to the total number of microglial cells was significantly higher in the intact, lesion and extensive diffuse MBP loss areas compared with the intact areas in the ischemia-normothermia group (p < 0.008, p = 0.001, p = 0.002)." (PMID 35690757, 2022). "There was a significant increase in MBP-labeled white matter area in the ischemia-normothermia group, compared with sham control (p = 0.042), which was significantly attenuated in the ischemia-hypothermia group (p = 0.015)." (PMID 35690757, 2022). "There was differential expression of microglia related to the severity of MBP loss, such that the greatest number of microglia in the white matter were found in the areas of intact MBP in the ischemia-normothermia group." (PMID 35690757, 2022). "The intact MBP area in the ischemia-hypothermia group had a significantly lower proportion of gitter cells compared with any area in the ischemia-normothermia group (p = 0.050, p = 0.001, p = 0.010)." (PMID 35690757, 2022). "The results of immunofluorescence showed that the MBP absorbance was lower in the CCH group than that in the sham group and gradually decreased with prolongation of the ischemia time, confirming that CCH caused white matter injury in a time-dependent manner." (PMID 35237278, 2022). "As regional patterns, carpets of densely packed MBP-positive structures were found to be primarily located in ischemia-affected basal and – to a much lesser degree – neocortical areas." (PMID 29467621, 2018). "While considering this concept, the present study applied a shell-like pattern to analyze MBP-immunoreactivity on the ischemia-affected hemisphere in comparison to the contralateral, non-affected hemisphere." (PMID 29467621, 2018). "MBP area fraction was significantly improved overall in both the ischemia-three-day and ischemia-five-day hypothermia groups (p < 0.05)." (PMID 27121655, 2016). "We found increased expression of NF200 and MBP in both the EC and peri‐infarct CTX areas of HT mice compared to NT mice, suggesting that selective brain cooling decreased myelin loss after ischemia." (PMID 36341958, 2023). "In the ischemia-hypothermia group, numbers of microglia were not significantly different between the areas of intact MBP or areas of localized diffuse MBP loss (p = 0.737), but still significantly higher than sham control (p = 0.001)." (PMID 35690757, 2022). "In addition, in the CA1 region following ischemia, myelin and vesicular synaptic density were significantly decreased as shown by immunohistochemistry for MBP and VGLUT-1." (PMID 34941848, 2021). "In addition, a significant (p < 0.05) decrease in the MBP-positive area on the 30th day after ischemia was found in the SR layer compared to the control." (PMID 32872364, 2020).
ischemia (continued). "MBP thus appeared as a robust marker for oligodendrocyte affection in the setting of experimental focal cerebral ischemia, at least when focusing on the early phase, i.e., 24 h after ischemia onset." (PMID 29467621, 2018). "In this context, the glial proteins myelin basic protein (MBP) and the 2′,3′-cyclic-nucleotide 3′-phosphodiesterase (CNP) as well as the vasculature-associated basement membrane proteins laminin and collagen IV have been identified as ischemia-sensitive elements." (PMID 37342767, 2023). "An increase in the area fraction of MBP labelling was seen in all hypothermia groups compared to ischemia-normothermia, to values that were not significantly different to sham controls." (PMID 31300687, 2019). "In contrast, the ischemia-five-day hypothermia group showed intermediate MBP integrity scores, which were not significantly different to either sham controls or to the ischemia-normothermia group in all regions (p > 0.05)." (PMID 27121655, 2016). "However, while ischemia-affected areas are characterized by a reduction of MAP2-related fluorescence intensity, an opposite effect as indicated by an increased intensity is observed for CNP, MBP, collagen IV, and laminin." (PMID 37342767, 2023).
ischemic stroke (16 papers, 2013 to 2025). A stroke disorder caused by obstruction of blood flow to the brain, due to thrombotic (local blood clot formation) or embolic (due to a blood clot or other material traveling from another site) event. "Oligodendrocyte death and myelin basic protein (MBP) loss have been described in hemorrhagic and ischemic stroke." (PMID 35150055, 2022). "To explore the effect of ADSC-EVs treatment on white matter injury after ischemic stroke in mice, we performed immunofluorescence staining of myelin marker MBP at 14 days after tMCAO." (PMID 35057862, 2022). "To understand why macrophage depletion facilitated the recovery of ischemic stroke, we examined MBP expression to assess the myelin lesion using immunostaining and western blot." (PMID 26873581, 2016). "Brain-specific MBP has been detected in the systemic circulation in nanogram concentration during the acute phase (e.g. hrs to few days) of ischemic stroke and are correlated with acute (24 hrs) or subacute (3 months) outcomes using targeted assays." (PMID 24752076, 2014). "To test whether BDMPs aggravate and Lactadherin treatment reduces axonal/WM injury after ischemic stroke in mice, we employed MBP, BS, and LFB staining to quantify WM changes in the cortex and striatum of IBZ." (PMID 31993045, 2019). "Furthermore, the breakdown of MBP and decrease in the myelin sheath thickness, post-ischemic stroke, which increases the vulnerability of exposed axons and leads to a decline in functional connectivity and behavioral deficits." (PMID 30283295, 2018). "There is evidence for T cell reactivity to autoantigens such as myelin basic protein (MBP) and myelin proteolipid protein (PLP) in patients with ischemic stroke." (PMID 31001280, 2019). "Ischemic stroke had no impact on myelin and phospholipids, and the ratio of SMI-32/MBP in the corpus callosum." (PMID 29167635, 2017).
viral infection (16 papers, 2011 to 2025). "Therefore, the results suggest that chronic TMEV infection led to the production of antibodies to MBP and other autoantigens in the CNS, which might represent autoantigens released following viral infection causing demyelination." (PMID 32727036, 2020). "The MBP expression reflected the formation of myelin fragments after demyelination, and the expression significantly increased in the early stage after virus infection and decreased at 15 dpi." (PMID 36441775, 2022). "MBP and peptide U24 of the HHV-6 viral particle share an identical sequence of 6 aminoacids (MBP residues 96–102, HHV-6 U24 residues 4–10), pointing at a possible contribution of viral infections to MS risk through molecular mimicry." (PMID 32431704, 2020). "The present study revealed that the proliferation of MBP-specific T-lymphocytes increases during JE viral infection." (PMID 21356046, 2011). "Furthermore, TMEV-infected SJL mice possessed elevated levels of autoantibodies to MBP, of which production was enhanced following viral infection." (PMID 32727036, 2020). "It was later shown that antibodies induced against Epstein-Barr latent membrane protein 1 during virus infection cross-react with MBP, and might act as inflammatory trigger by reacting with MBP." (PMID 31850365, 2019). "In a mouse model of autoimmune encephalitis employing a dual TCR specific for an exogenous viral antigen and myelin basic protein viral infection could brake tolerance to MBP and induce autoimmune pathology hinting to such a mechanism in humans as well." (PMID 22649519, 2012). "In addition, peripheral blood MNC from MS patient subjects can also react to viral- and myelin basic protein (MBP)-specific peptide fragments, but the direct causal links between these virus infections and predisposition to MS have not been proved clinically in a large number of cases." (PMID 24879066, 2014). "Disease was also triggered in mice after infection with the wild type Vaccinia vector which did not contain MBP but immunisation with peptide plus adjuvant only did not trigger disease, indicating that viral infection was necessary to break tolerance to CNS antigens in these models." (PMID 38022632, 2023). "It is possible that reactivation of the memory T cells, by another injury or perhaps by other neuroinflammatory stimulus, such as bacterial or viral infections, might re-open the BBB and expose the memory immune cells to self-antigens, such as GFAP, UCH-L1 or MBP." (PMID 28124982, 2017).